XBP1 (X-box binding protein 1)
Diseases named in the same sentence as XBP1 in open-access papers (continued):
Sharing a sentence is not in itself a finding about the gene and the disease.
ovarian carcinoma (continued). "Importantly, XBP1 alteration is significantly related to multiple immune checkpoints at a genomic level, which strongly suggests a possible co-contribution to immune surveillance and evasion of ovarian cancer." (PMID 35991556, 2022). "Furthermore, XBP1-s also drives the progression of ovarian cancer by disrupting DC function." (PMID 35269888, 2022). "Interestingly, based on gene expression, prognosis, and relativity to multiple immune checkpoints analyses, we found that XBP1-based therapy may show a more promising prospect for ovarian cancer immunotherapy than immune checkpoint inhibitors therapy." (PMID 35991556, 2022). "Thus, it can be concluded XBP1 is a potential coregulator of immune checkpoints in ovarian cancer." (PMID 35991556, 2022). "The relationship between the ratio of XBP1/ACTB mRNA expression and clinicopathological parameters in ovarian cancer tissues." (PMID 40105652, 2025). "The results revealed that XBP1 is highly expressed in ovarian cancer in comparison to the normal control tissue and high XBP1 expression largely favored the OS and DFS of ovarian cancer patients." (PMID 35991556, 2022). "Here, we evaluated the effect of miR-30c-2-3p on controlling XBP1-CHOP-BIM and its apoptotic effects on ovarian cancer cell lines during ERS." (PMID 34121978, 2021). "Supporting activation of the IRE1α branch of the UPR, in PEO-4 ovarian cancer cells, BHPI and E2 robustly induced sp-XBP1." (PMID 29599904, 2018). "Mice with ovarian cancer that lacked either IRE1 alpha or XBP1 specifically in T cells also showed a decrease in malignant progression and an improvement in survival rates through the reprogramming of intratumoral T cells." (PMID 40035165, 2025). "In conclusion, upregulating XBP1 rather than targeting immune checkpoints represents a potentially more efficient approach for ovarian cancer therapy." (PMID 35991556, 2022). "We found that XBP1 was significantly correlated with key immunity-killing molecules, including FASL, PRF1, IFNG, GZMB, TNFa, and CD40L in ovarian cancer." (PMID 35991556, 2022). "Among these transcription factors, SP1 is overexpressed in ovarian cancer, while there are no prior studies on the expression of NF-YA and XBP-1 in ovarian cancer (OncomineTM database)." (PMID 29262583, 2017). "In ovarian cancer models, DCs lacking XBP1 slowed cancer progression." (PMID 40547943, 2025). "In ovarian cancer, FOXK2, as a highly expressed stemness-specific transcription factor, increased stemness features and tumour initiation capacity by directly activating the IRE1α-XBP1 pathway, while genetic or pharmacological blockade of this pathway inhibited ovarian CSCs." (PMID 38297380, 2024). "Consistent with our previous findings using SpiD7 in ovarian cancer models, SpiD3 treatment activated sustained UPR signaling in CLL cells evidenced by an accumulation of unfolded proteins, PERK activation, and increased expression of ATF4, CHOP, and spliced XBP1." (PMID 38687198, 2024). "Thus, upregulating XBP1 rather than targeting immune checkpoints represents a potentially more efficient approach for ovarian cancer therapy." (PMID 35991556, 2022). "Interestingly, xenografting of the ovarian cancer cells into NSG mice did not lead to a significant increase in IRE1α activation or splicing of XBP-1." (PMID 33718372, 2021). "In this study, our results showed the expression, prognosis, and relativity to antitumor immunity analyses of immune checkpoints may not be ideal therapeutic targets for ovarian cancer, and XBP1 is a potential coregulator of immune checkpoints in ovarian cancer." (PMID 35991556, 2022).
colitis (37 papers, 2011 to 2026). Inflammation of the colon. "In these mice, Xbp1 deletion causes spontaneous enteritis and increased susceptibility to induced colitis secondary to defects in Paneth cells and goblet cells." (PMID 33557139, 2021). "First, there is clear genetic and functional evidence for a role of ER stress in IBD, such as the findings that loss of XBP1 is known to result in colonic inflammation." (PMID 31227842, 2019). "For example, deletion of XBP1 in intestinal epithelial cells results in spontaneous enteritis and increased susceptibility of experimental colitis, reflecting the crucial role of constitutive XBP1 expression in intestinal epithelial cells." (PMID 25754093, 2015). "The epithelial-specific deletion of XBP1 in mice resulted in spontaneous ileitis and increased susceptibility to chemically induced colitis." (PMID 22028783, 2011). "Epithelial-specific deletion of XBP1 in mice resulted in spontaneous ileitis and increased susceptibility to chemically induced colitis, linking cell-specific ER stress to organ-specific inflammation." (PMID 22028783, 2011). "XBP1 deletion → spontaneous enteritis, Paneth cell dysfunction, ↑ colitis susceptibility." (PMID 41383462, 2025). "While the IL-23-IRE1α/XBP1 pathway in ILC3s may be protective in colitis, other IL-23 targets including JAK2 and TYK2 are pathogenic." (PMID 38722686, 2024). "This may explain why the loss of IRE1α/XBP1 in ILC3s exacerbates colitis in mice, while global suppression of IL-23 benefits a subset of patients with IBD." (PMID 38722686, 2024). "Furthermore, the XBP1 knockout mice (XBP1−/−) showed reduction in microbial killing, increase of susceptibility to dextran sodium sulfate-induced colitis." (PMID 29323257, 2018). "Furthermore, it was shown that ER stress and dysregulated autophagy process act synergistically to promote UC development, following the observation that mice deficient for both Atg16L1 and Xbp1 developed an increased intestinal inflammation and a severe form of colitis." (PMID 32659925, 2020). "Furthermore, Xbp1−/− mice show an increased susceptibility to DSS-induced colitis." (PMID 24498426, 2014). "muciniphila alleviates DSS-induced colitis by targeting inositol requiring enzyme 1α(IRE1α) and unspliced XBP1 (XBP1u) within the ER stress pathway, with the regulation of XBP1u being FXR-dependent." (PMID 41459926, 2025). "The expression levels of IDO1, GRP78 and XBP1 were significantly elevated during the acute colitis phase of UC in the four GEO cohorts." (PMID 40370742, 2025). "To explore the involvement of IRE1α/XBP1 in intestinal ILC3s beyond acute colitis models, we conducted a T cell transfer–induced colitis experiment, which represents a chronic immune-mediated model of IBD." (PMID 38722686, 2024). "IRE1α/XBP1 activation in ILC3s occurred in mice exposed to dextran sulfate sodium–induced (DSS-induced) colitis, while intestinal specimens from patients with IBD expressed higher levels of XBP1s than did healthy controls." (PMID 38722686, 2024). "Specifically, in TNBS-induced colitis, Cd44, Numa1, S100a8, S100a9, Timp1 and Xbp1 were more highly expressed, while Cidec and Rag1 were less expressed." (PMID 38778086, 2024). "IRE1α/XBP1 was activated in ILC3s from mice exposed to experimental colitis and in inflamed human IBD specimens." (PMID 38722686, 2024). "Additional research is required to determine the underlying mechanisms by which IRE-1/XBP-1 regulates gut epithelium differentially in GVHD and colitis models." (PMID 37744326, 2023). "Studies found that ERS increased and goblet cells decreased in Xbp1−/− mice, which decreased MUC 2 secretion and enhanced susceptibility to experimental colitis." (PMID 34588980, 2021). "IEC-specific XBP1 deletion resulted in ER stress (IRE1-XBP1 axis), spontaneous inflammation and an increased susceptibility to dextran-sodium sulfate (DSS)-induced colitis." (PMID 31867005, 2019).
colitis (continued). "In colonic mucosal tissues from mice and humans, Xbp1 was targeted by a colitis-induced miRNA, miR665, which was shown to promote apoptosis and DSS-induced colitis in mice." (PMID 30026758, 2018). "Consistently, GP supplementation reduced the protein expression of ATF-6 and mRNA expression of its downstream target genes Grp78, CHOP, Edem1, and Xbp1 in the HFD-fed DSS-colitis mice, showing the suppression of ER stress." (PMID 28524086, 2017). "IHC staining demonstrated that (±)-8-ADC treatment decreased NF-κB and increased XBP1 expression levels following DSS-induction of colitis." (PMID 28928666, 2017). "Overall, (±)-8-ADC significantly inhibited the development of colitis and improved the pathology associated with acute colitis induced by DSS by acting via the XBP1-NF-κB pathway." (PMID 28928666, 2017). "Of note, conditional inactivation of Xbp1 in the intestine results in spontaneous colitis, and, in IBD patients, increased levels of Xbp1-s were described." (PMID 29069719, 2017). "This present study was undertaken to investigate the mechanism of action of (±)-8-ADC prevention of the development of colonic inflammation, and it was found to act via the XBP1-NF-κB pathway in a DSS-induced colitis mouse model and the IEC6 cell line." (PMID 28928666, 2017). "Dr. Blumberg’s group reported that mice with tissue-specific deletion of XBP1 in IECs developed spontaneous enteritis and displayed increased susceptibility to DSS-induced colitis." (PMID 25120559, 2014). "Mice with epithelial-specific ablation of Xbp1 or IκB kinase-γ (NEMO) have significant α-defensin deficiencies and increased susceptibility to colitis." (PMID 22384242, 2012). "Additionally, inhibition of the IRE1α–XBP1 pathway or blocking exosome release using GW4869 has been shown to mitigate colitis severity, providing functional validation of this mechanism." (PMID 41383462, 2025). "We next examined IRE1α/XBP1 activation in colonic ILC3s in the DSS-induced model of colitis." (PMID 38722686, 2024). "MiR‐665 enhances cell apoptosis and colitis through inhibiting XBP1 in inflammatory bowel disease." (PMID 36705422, 2023). "Inhibition of miR-330-3p showed a significant upregulation of XBP1 expression and reduction of weight loss and DAI elevation in DSS-induced colitis, which is consistent with the previous finding that activation of XBP1 inhibited the pathogenesis of ulcerative colitis." (PMID 32386518, 2020). "Hence, Xbp1 knockdown mice with induced colitis displayed an increased grp78 expression, as well as depletion of a large number of goblet and Paneth cells." (PMID 32659925, 2020). "This dissociation activates ATF6, PERK and IRE-1 and its related downstream signaling, which regulates the release of ER-stress associated transcription factors from the nucleus such as C/EBP homologous protein (CHOP) and X-box binding protein 1 (XBP-1), leading to the development of colitis." (PMID 32998266, 2020). "XBP1 is genetically associated with UC, where deletion of XBP1 affects the intestinal epithelium and results in spontaneous intestinal inflammation and XBP1ΔIEC mice have aggravated dextran sodium sulfate (DSS)-induced colitis compared to wild-type mice." (PMID 28928666, 2017). "Furthermore, genomic deletion of Xbp1 or Ire1β, which are both ER stress-related genes, increases susceptibility to DSS-induced colitis." (PMID 24498426, 2014). "The involvement of IRE1 pathway in colitis is also supported by XBP1 conditional KO mice." (PMID 25120559, 2014). "Besides influencing apoptosis and inflammation via autophagy regulation, a recent study showed that upregulation of miR-665 promotes apoptosis and colitis in inflammatory bowel disease by repressing the endoplasmic reticulum (ER) stress components XBP1 and ORMDL341." (PMID 29706629, 2018).
colitis (continued). "Subsequently, DSS-induced colitis was used to measure the level of IDO1, GRP78, XBP1, and M1 marker iNOS correlated with disease activity, while 1MT treatment ameliorated DSS-induced colitis by downregulating IDO1-GRP78-XBP1 pathway." (PMID 40370742, 2025). "ILC3s exposed to inflammatory cytokines, experimental colitis, and IBD selectively activate IRE1α/XBP1." (PMID 38722686, 2024). "To investigate if the UPR could directly induce HMGCS2 downregulation in vivo, we injected tunicamycin in C57BL/6 wild type mice as well as in Xbp1ΔIEC mice, which display a defective UPR through the deletion of Xbp1 in IECs resulting in an ER associated spontaneous enteritis, but not colitis." (PMID 37457727, 2023). "Thus ERS-induced mucin depletion seems to be a relevant pathogenetic mechanism of colitis in IL-10 deficient mice; our results demonstrating a significantly reduced number of goblet cells and expression of MUC-2, IL-18, WFDC2 and Xbp-1 in IL-10 deficient mice at young ages support this hypothesis." (PMID 36699599, 2022). "In fact, compared with Atg16L1[ΔIEC] or Xbp1[ΔIEC] mice, mice lacking Atg16L1 and Xbp1 (Atg16l1[ΔIEC]Xbp1[ΔIEC]) develop more severe colitis." (PMID 34588980, 2021). "It was not surprising that the expression levels of CIDEC, NUMA1 and RAG1 in human subjects; Ndrg1 and Pea15a in mice with TNBS-induced colitis; and Cidec, Pea15a and Xbp1 in mice with DSS-induced colitis were not significantly different given the small sample sizes." (PMID 38778086, 2024). "However, several pieces of evidence suggested that Xbp1 deletion in mouse intestinal epithelial cells resulted in Paneth and goblet cell apoptosis, spontaneous ileal inflammation, and increased sensitivity to dextran sodium sulfate (DSS)-induced colitis." (PMID 38516345, 2023).
diabetes (37 papers, 2009 to 2025). "XBP1 expression colocalises with diabetes risk in East Asians but not in white Europeans, and lower expression is associated with higher risk of diabetes." (PMID 40993285, 2025). "This study aimed to evaluate the impact of XBP1 expression on diabetes risk, beta-cell function, glycaemic traits, and treatment response across ancestries." (PMID 40993285, 2025). "CHOP is induced predominantly by the PERK/eIF2α/ATF4 signaling cascade associated with ER stress, as well as by the IRE1α/Xbp-1 signaling pathway and the ATF6α transcription factor in different pathological conditions, including diabetes." (PMID 34834808, 2021). "Selection conversion suggests that protective alleles for increased XBP1 expression have been selected for to a greater degree in Europeans, who also have a lower risk of beta-cell dysfunction and therefore lower frequency of young and lean onset diabetes." (PMID 40993285, 2025). "The transcription factor XBP1 supports beta-cell survival by reducing cellular stress, but its role in diabetes risk and glucose regulation remains unclear." (PMID 40993285, 2025). "Xbp1 is a very complex protein regulating many physiological functions, including immune system, inflammatory responses, lipid metabolism, neurodegeneration, diabetes and is implicated in AD." (PMID 35860672, 2022). "Similar to diabetes, XBP1 signaling is implicated in Wolfram syndrome." (PMID 34063979, 2021). "The spliced XBP1 transcription factor has been broadly reported as a key element of regulation of gene expression and has been shown to be implicated in multiple pathological conditions including diabetes, Alzheimer’s disease and various types of cancer." (PMID 32774853, 2020). "Hence, a deficiency in BI-1 resulting in unrestrained IRE1α/XBP1 signaling may predispose to pancreatic islet loss, a hallmark of early-onset diabetes that can be exacerbated upon diet-induced diabetes." (PMID 38744890, 2024). "The loss of the XBP1 function in diabetes may enhance IRE1α activity." (PMID 35455399, 2022). "Conditional knockout of XBP1 in retinal neurons leads to early onset retinal function decline, neuronal loss, and enhanced Müller glia activation in diabetic mice, suggesting that the XBP1 pathway is critical for neuronal protection against diabetes induced retinal injury and dysfunction." (PMID 35346303, 2022). "Disruption of the IRE‐1α/XBP1 pathway impairs proinsulin synthesis and increases oxidative stress, contributing to β‐cell dysfunction and the development of diabetes." (PMID 40145401, 2025). "They identified XBP1 as a key transcription factor that was down-regulated in individuals with diabetes compared to those with pre-diabetes and healthy controls, which sensitizes beta-cells to ER stress." (PMID 40993285, 2025). "Our current data reveal that unresolved ER stress triggers a terminal UPR with sustained activity of IRE1α-XBP1-CHOP signaling that promotes programmed cell death, leading to pancreatic injury and diabetes in BI-1-deficient mice." (PMID 38744890, 2024). "This is further supported by the fact that many of the closely correlating protein-coding genes have themselves been previously implicated in diabetes, such as FAIM2, JAZF1, and XBP1, as well as others whose connections likely remain uncharacterized." (PMID 37218990, 2023). "In summary, we present the first evidence that XBP1 maintains mature beta cell identity, represses beta-to-alpha cell transdifferentiation and is required for beta cell protection against diabetes in insulin resistance states." (PMID 35316840, 2022). "Nevertheless, in experimental models of chronic streptozotocin-induced diabetes, podocyte-specific deletion of XBP1 or inducible activation of ATF6 aggravated features of DN." (PMID 35455399, 2022). "Xbp1 deletion in beta cells of obese ob/ob or high-fat diet-fed mice triggered diabetes and worsened glucose intolerance by disrupting insulin secretory capacity." (PMID 35316840, 2022).